WFDC10B (WAP four-disulfide core domain 10B)
Synonyms: WAP12
Tractability: Antibody: UniProt places it where antibodies can reach, with high confidence; UniProt predicts a signal peptide or a membrane-spanning region; its Gene Ontology location is reachable by antibodies, with medium confidence.
Gene: Protein-coding gene on chromosome 20 (45,684,651 to 45,705,019, reverse strand). Ensembl gene ENSG00000182931.
Subcellular location: Secreted
Subcellular location (Human Protein Atlas): Vesicles; Predicted to be secreted
Gene Ontology:
Molecular function: protein binding; serine-type endopeptidase inhibitor activity; peptidase inhibitor activity
Biological process: antibacterial humoral response; innate immune response
Cellular component: extracellular region
Genetic constraint (gnomAD): Loss-of-function variants: 1 observed, 2.92 expected, observed/expected ratio (o/e) 0.34, 90% interval 0.12 to 1.49. That is too few expected variants to judge how well the gene tolerates losing a copy. Missense variants: 71 observed, 91.57 expected, observed/expected ratio (o/e) 0.78, 90% interval 0.64 to 0.94. Synonymous variants: 26 observed, 33.76 expected, observed/expected ratio (o/e) 0.77, 90% interval 0.56 to 1.07.
Homologues: Orthologues: macaque WFDC10B (90% identical), Drosophila melanogaster CG5639 (23% identical), Caenorhabditis elegans C08G9.2 (14% identical). Paralogues in human: WFDC10A (70% identical), WFDC9 (34% identical), WFDC11 (30% identical), WFDC13 (30% identical), WFDC3 (27% identical), WFDC5 (26% identical), PI3 (21% identical), WFDC12 (21% identical), SLPI (18% identical).
Diseases named in the same sentence as WFDC10B in open-access papers:
WFDC10B is named in the same sentence as 1 disease in open-access papers, as found by Europe PMC text mining. Sharing a sentence is not in itself a finding about the gene and the disease. The quoted sentences say what the papers report.
colon carcinoma (1 paper, 2022). "Expression of WFDC10B significantly upregulated in the hepatic metastasis of colon carcinoma." (PMID 35795065, 2022).